ENSG00000289258 (novel protein)
Gene: Protein-coding gene on chromosome 10 (86,654,518 to 86,700,020, forward strand). Ensembl gene ENSG00000289258.
Genetic constraint (gnomAD): Loss-of-function variants: 66 observed, 82.47 expected, observed/expected ratio (o/e) 0.8, 90% interval 0.65 to 0.98. Missense variants: 1,069 observed, 1,095 expected, observed/expected ratio (o/e) 0.98, 90% interval 0.93 to 1.03. Synonymous variants: 454 observed, 439.25 expected, observed/expected ratio (o/e) 1.03, 90% interval 0.96 to 1.12.